TXNIP (thioredoxin interacting protein)
Diseases named in the same sentence as TXNIP in open-access papers (continued):
Sharing a sentence is not in itself a finding about the gene and the disease.
diabetes (continued). "Further, we observed that diabetes increases TXNIP expression significantly (P<0.007) both in message and protein levels in the rat retina when compared with the non-diabetic rat retina." (PMID 28492550, 2017). "Collectively, these results indicate that inhibition of TXNIP attenuates diabetes-induced inhibition of tubular autophagy in diabetic rat kidneys." (PMID 27381856, 2016). "Since deleting the gene for TXNIP diminished this effect, they propose that diabetes increases fructose absorption and that TXNIP is involved in this process." (PMID 27725088, 2016). "Previous studies have shown that diabetes leads to increased production of TXNIP and that deleting the gene for TXNIP (or otherwise inhibiting the protein) can prevent diabetes, improve glucose tolerance and have a beneficial effect on glucose metabolism." (PMID 27725088, 2016). "Thioredoxin-interacting protein (Txnip/VDUP1/TBP-2) was originally discovered as a vitamin D3-inducible gene but has gained recent interest for being involved in diabetes, hyperlipidemia, carcinogenesis, cardiac function, angiogenesis, and inflammation." (PMID 27437069, 2016). "The researchers also found that triggering diabetes in mice (by killing their insulin-producing cells with a toxin called streptozotocin) led to more TXNIP being produced in the small intestine." (PMID 27725088, 2016). "Beta-cell thioredoxin-interacting protein (TXNIP), a cellular redox regulator upregulated in diabetes, induces the expression of miR-204." (PMID 27438705, 2016). "TXNIP expression is markedly upregulated in human diabetes and diabetic complications, indicating that TXNIP is a potential therapeutic target of diabetes." (PMID 27867451, 2016). "Animals with diabetes mellitus demonstrated a marked increase in renal interstitial collagen deposition (P < 0.01), while inhibition of TXNIP with DNAzyme significantly reduced diabetes-induced excessive matrix deposition (P < 0.05)." (PMID 27381856, 2016). "Inhibition of TXNIP with DNAzyme significantly attenuated diabetes-induced upregulation of LC3 expression in the renal tubule cells of diabetic rats (P < 0.05)." (PMID 27381856, 2016). "Thioredoxin-interacting protein (TXNIP) is an early response gene highly induced by diabetes and hyperglycemia." (PMID 26881256, 2016). "TXNIP inhibition suppressed diabetes-induced BNIP3 expression and activation of the mTOR signaling pathway." (PMID 27381856, 2016). "The rs7211 polymorphism in TXNIP was associated with inhibition of TNX, glucose homeostasis, diabetes, and hypertension." (PMID 27274779, 2016). "Thioredoxin can bind to signalling molecules such as ASK-1 and TXNIP that potentially influence cell growth and survival in diverse human diseases such as cancer, diabetes, and heart disease 19,20." (PMID 25858687, 2015). "Silencing TXNIP expression in adipocytes and in skeletal muscle was found to enhance glucose uptake, and TXNIP was also elevated in muscles of prediabetics and diabetics." (PMID 23691179, 2013). "Thioredoxin Interacting Protein (TXNIP) mediates retinal inflammation, gliosis, and apoptosis in experimental diabetes." (PMID 22474421, 2012). "TXNIP is considered as a pro-oxidative stress, pro-inflammatory, and proapoptotic protein under chronic hyperglycemia, diabetes, and cellular stress." (PMID 22474421, 2012). "TXNIP is upregulated by glucose and is a critical mediator of hyperglycemia-induced beta-cell apoptosis in diabetes." (PMID 22194917, 2011). "Of relevance to the fate of beta-cells in diabetes, TXNIP expression is robustly induced by glucose in islets." (PMID 22194917, 2011). "Although various studies have recently addressed the relevance of TXNIP in cancer biology, our study is the first one relating this protein to metabolic conditions of hyperglycemia/diabetes and oxidative stress in the same context." (PMID 17555594, 2007). "In individuals with diabetes or prediabetes, TXNIP expression is elevated." (PMID 40926986, 2025).
diabetes (continued). "Nevertheless, studies indicated molecular crosstalk between TXNIP and Snhg15 during diabetes." (PMID 41144575, 2025). "Epigenetic control of TXNIP expression seems to be one of the mechanisms that could be targeted and regulated to affect the severity of diabetes." (PMID 40725425, 2025). "Bone health is affected by diabetes through different mechanisms, among others, and particular attention should be kept towards VDR polymorphisms, Vitamin D, incretins, GLP-2, neurotensin, asprosin, irisin, and TXNIP levels." (PMID 40943066, 2025). "TXNIP is traditionally identified to participate in the pathogenesis of various human diseases such as kidney disease, neurodegeneration, and diabetes; however, emerging studies reveal that it also plays critical roles in regulating inflammation, oxidative stress, pyroptosis and tissue injury." (PMID 40061945, 2025). "Moreover, TXNIP has been correlated with typical complications of diabetes, such as diabetic nephropathy or vascular complications." (PMID 40725425, 2025). "In line with this hypothesis, the expression of TXNIP has been correlated with the pathophysiology of diabetes." (PMID 40725425, 2025). "The link between hyperglycemia and TXNIP in diabetes has been extensively documented in pancreatic beta cells and in insulin target tissues, involving mechanisms of glucose-stimulated insulin secretion and sensitivity, glucose uptake, beta cell apoptosis, and inflammation." (PMID 40559375, 2025). "Consequently, the role of Vitamin D, Incretins, Glucagon-like peptide-2 (GLP-2), neurotensin, asprosin, irisin, and Thioredoxin-interacting protein (TXNIP) will be described considering the interplay between diabetes and bone health." (PMID 40943066, 2025). "TXNIP gene expression has been found to be upregulated in skeletal muscle samples from individuals with diabetes and prediabetes, supporting our hypothesis." (PMID 39827095, 2025). "Tissue-specific overexpression of FoxO1 in transgenic mouse models conferred renal protection, partly by attenuating diabetes-induced increases in Thioredoxin Interacting Protein (TXNIP) and reducing Thioredoxin (TRX) levels, thereby partially reversing renal interstitial fibrosis and apoptosis." (PMID 39382800, 2024). "Importantly, TXNIP is not only induced by glucose in vitro, but pancreatic islet TXNIP expression is also elevated in vivo in various diabetes mouse models as well as in islets and beta cells of subjects with T1D and T2D." (PMID 39429740, 2024). "Notably, circulating free fatty acids such as those resulting from consuming a Western diet or having diabetes, induce mitochondrial ROS in muscle, which leads to over-expression of TXNIP, reduced glucose uptake, and hyperglycemia." (PMID 39867556, 2024). "Indeed, several studies showed that verapamil treatment reduced the pro-apoptotic TXNIP expression, thereby promoting the survival of β-cells and preventing diabetes." (PMID 38891081, 2024). "This study sought to explore the clinical relevance of the associations of serum levels of advanced glycation end products (AGEs), soluble receptor for AGEs (sRAGE), and thioredoxin-interacting protein (TXNIP) with the renal fat fraction (RFF) in individuals with type 2 diabetes mellitus (T2DM)." (PMID 38951835, 2024). "However, further clinical trials and prospective cohort studies are needed to elucidate the role of AGEs and TXNIP in the occurrence of heterotopic renal fat deposition and diabetes-related complications in patients with T2DM." (PMID 38951835, 2024). "Other notable inhibitors such as SRI-37330, DI-NBP, W2476, quercetin, allopurinol, and salidroside have demonstrated promising effects across various disease models, including diabetes, nonalcoholic fatty liver disease, and diabetic nephropathy, targeting different mechanisms of TXNIP action." (PMID 38790650, 2024).
diabetes (continued). "Although some studies on serum TXNIP levels in patients with diabetes have yielded consistent results, there is insufficient evidence on whether it can be used as a serum marker in patients with diabetes or DKD." (PMID 37144033, 2023). "Methylation of the TXNIP gene (thioredoxin-interacting protein) and KCNQ1 (potassium voltage-gated channel subfamily Q member 1) was previously shown to associate with the development of diabetes complications." (PMID 36633903, 2023). "Recent studies have suggested the key effect of TXNIP on lipid metabolism during diabetes." (PMID 37144033, 2023). "TXNIP expression, when reduced, promotes beta-cell mass and survival and protects against diabetes." (PMID 37296593, 2023). "Furthermore, an orally available chemical compound that can provide a distinct approach to treat diabetes with TXNIP regulation has been reported very recently." (PMID 36733403, 2023). "Therefore, the ability of bioactive dietary plant compounds to target and inhibit TXNIP signaling has profound therapeutic implications in diabetes management." (PMID 39319322, 2023). "Subsequently, MIN6 cells were treated with a cytokine mixture of TNF-α, IL-1β and IFN-γ in the presence or absence of UC, and verapamil, a TXNIP inhibitor for prevention of beta cell loss and diabetes development, was used as a positive control in this study." (PMID 38040681, 2023). "Although in-depth studies of this intracellular signaling pathway in the DKD state are lacking, it has been demonstrated that FOXO1 can suppress NLRP3 inflammasome activation by reducing the TXNIP level in patients with diabetic atherosclerosis and diabetic liver." (PMID 37144033, 2023). "If TXNIP is in fact the master regulator of glucose homeostasis, then a question that requires investigation is whether those postbariatric surgery patients with diabetes relapse showed a reelevated TXNIP level." (PMID 36733403, 2023). "However, further studies are needed to elucidate SNHG15 lncRNA effect on the TXNIP expression pattern in diabetes." (PMID 37462767, 2023). "The regulation of TXNIP, miR-204, and MafA might play an important role in the mechanism of diabetes remission following bariatric surgery." (PMID 36733403, 2023). "Collectively, hypomethylation of the two CpG sites in TXNIP identified through EWAS analysis suggests that it may play an important role in the pathogenesis of diabetes mellitus in the Korean population." (PMID 38137029, 2023). "High glucose in diabetes induces production of TXNIP resulting in β-cells apoptosis." (PMID 39319322, 2023). "Consequently, TXNIP antagonists are candidates for treating diabetes and neurological diseases, whereas TXNIP agonists hold potential for cancer treatment." (PMID 37794178, 2023). "Moreover, several experts have elucidated the mechanism of TXNIP in the progression of diabetes and its role in the treatment of diabetes." (PMID 37144033, 2023). "In addition, we found that sitagliptin prevented the upregulation of TXNIP (a prooxidant and proapoptotic protein) induced by diabetes, which plays a relevant role in the pathogenesis of DR." (PMID 35883908, 2022). "In addition to c-JUN, which is induced by oxidative stress, another important factor that can deteriorate β-cell function via the downregulation of MAFA during diabetes is TXNIP, a cellular redox regulator." (PMID 35562869, 2022). "The expression of TXNIP is increased in the retina, pancreas, kidney, heart, peripheral nerves, and many other organs in patients with diabetes." (PMID 36017183, 2022). "However, under pathophysiological conditions, such as diabetes, TXNIP is continuously induced by many factors, such as high glucose levels, causes β-cell dysfunction, and breaks this feedback loop." (PMID 36017183, 2022). "Finally, the direction of association for CPT1A, ABCG1, SOCS3, TXNIP and SREBF1 was consistent with that reported in the literature for MetS and/or diabetes." (PMID 34780523, 2021).
diabetes (continued). "Indeed, targeting TXNIP helps to counter the deleterious effects of diabetes through improved reperfusion of the ischemic limb, reduction of tissue damage, and increased capillary density." (PMID 33567593, 2021). "Nonetheless, TXNIP expression is reciprocally associated with glucose transporter 1 (Glut1) in prostate cancer, whereas in diabetes, it also activates the negative-feedback loop to regulate glucose assimilation in response to a rise in glucose concentration." (PMID 33803178, 2021). "In this review, ERS activates NLRP3 inflammasome through the ROS/TXNIP pathway in diabetes." (PMID 33937267, 2021). "Studies showed that TXNIP inhibition prevented β-cell apoptosis and protected against diabetes." (PMID 34500775, 2021). "TXNIP expression is highly triggered by glucose and is increased in the beta-cells (β-cells) of patients with diabetes, inhibiting TXN function and inducing increased levels of freely diffusible molecular hydrogen peroxide; it contributes to oxidative stress and eventually β-cell death." (PMID 34500775, 2021). "TXNIP is an important binding partner of Trx and forms a Trx/TXNIP signaling complex (known as redoxisome), which is an evolutionarily conserved reduction–oxidation (redox) signaling complex that plays a significant role in pathophysiology, including diabetes." (PMID 34401074, 2021). "Devi and colleagues reported induction of mitochondrial damage and mitophagy in rMCs exposed to HG that were mediated by the upregulation of thioredoxin-interacting protein (TXNIP), a pro-oxidative stress and pro-apoptotic protein strongly induced by diabetes and HG conditions." (PMID 34234681, 2021). "However, in diabetes and under high glucose, we have shown that a protein called thioredoxin-interacting protein (TXNIP) is strongly induced in most cells examined, including retinal and renal cells." (PMID 35187384, 2021). "The team shows that the angiogenesis defect attributed to diabetes is dependent on TXNIP." (PMID 33567593, 2021). "Further investigation of redox-dependent and -independent scaffolding functions of TXNIP may give us deeper insights of the molecular functions of TXNIP in pathophysiology and future therapeutics for diabetes." (PMID 32824669, 2020). "Taking abnormal NCV as the dependent variable, and TXNIP, age, course of diabetes, FBG, HbA1c, vitamin D3, and SDBG as independent variables, regression analysis showed that the risk factors for NCV abnormality in T2DM patients were age, course of diabetes, FBG, SDBG, vitamin D, and TXNIP." (PMID 32774321, 2020). "Recent evidences demonstrated that carbohydrate response element-binding protein (Chrebp)/Thioredoxin-interacting protein (Txnip) signaling played central roles on diabetes progression, particularly in relation to the function maintenance and apoptosis of pancreatic β-cell." (PMID 31956333, 2020). "Further studies are needed on human brains from cases with diabetes to determine whether there is increased expression of TXNIP and whether this is correlated with AD or severity of AD pathology." (PMID 33302545, 2020). "TXNIP is a negative regulator of anti-oxidation and is involved in diabetes." (PMID 33584307, 2020). "It has been proposed that TXNIP inhibition could be a novel approach for β-cell death protection, β-cell mass promotion and diabetes prevention." (PMID 31708773, 2019). "Because TXNIP is the strongest glucose-responsive gene in pancreatic β-cells, TXNIP may be a potential therapeutic target in the treatment of diabetes." (PMID 31835423, 2019). "Nonetheless, other pathways, including BNIP3L/NIX or TXNIP, might also be important for orchestrating mitophagy in diabetes." (PMID 31661466, 2019). "Interestingly, the auxiliary activation agent of inflammasome thioredoxin-interacting protein (TXNIP) involved in ROS is closely related to the occurrence of diabetes." (PMID 30704457, 2019). "TxnIP may itself also influence endothelial dysfunction in diabetes by inducing histone modifications." (PMID 29934664, 2018).
diabetes (continued). "In addition to diabetes, TXNIP is also known to be upregulated in age-related neurodegenerative diseases such as Alzhemer’s and Parkinson’s diseases and Amyotrophic lateral sclerosis (ALS)." (PMID 31355358, 2018). "TXNIP expression is induced by glucose and its level is pathologically elevated in diabetes." (PMID 30524286, 2018). "The idea that a TXNIP promoter construct could be used for gene and tissue engineering of adipose stem cells for the treatment of diabetes and its complications is innovative and will be practical if and when the proof of concept of this method is validated." (PMID 31355358, 2018). "Similarly, mRNA and protein expression levels of TXNIP have been found to be higher in the tumoral tissues of pancreatic cancer patients with diabetes." (PMID 30627326, 2018). "TXNIP is a possible therapeutic target for diabetes and its related vascular complications." (PMID 29507694, 2018). "TXNIP gene expression is stimulated by glucose and suppressed by insulin in a variety of cells and tissues, including skeletal muscle and adipose tissue and cells, and TXNIP gene expression is upregulated in skeletal muscle samples from subjects with diabetes and prediabetes." (PMID 29077742, 2017). "In this study, we were unable to confirm our a priori hypothesis of decreased TXNIP DNA methylation and increased gene expression in adult offspring of women with diabetes in pregnancy compared to controls." (PMID 29077742, 2017). "TXNIP is induced early by hyperglycemia (in vitro) and diabetes (in vivo diabetic retina)." (PMID 28815013, 2017). "However, this study opens the gate to new researches about the role of HMOX1, TXNIP, and Nrf2 in obesity, diabetes, and worse metabolic traits." (PMID 27274779, 2016). "Additionally, we sought to determine the effect of TXNIP and elucidated its relationship to NLRP3 inflammasome activation in the susceptibility to ischemic AKI in diabetes." (PMID 27867451, 2016). "In addition, experimental evidence has indicated that hyperglycemia can induce TXNIP expression in renal tubular epithelial cells, and diabetes can potentially enhance TXNIP expression and reduce TRX activity." (PMID 27867451, 2016). "Indeed, the data show that TXNIP links fructose absorption to both glucose homeostasis and diabetes." (PMID 27725088, 2016). "Herein, we examined the impact of diabetes mellitus on thioredoxin-interacting protein (TXNIP) expression and whether mediated NLRP3 activation was associated with renal ischemia/reperfusion- (I/R-) induced AKI." (PMID 27867451, 2016). "RNAi silencing TGS of TXNIP abolishes diabetes-induced retinal gliosis and ganglion injury." (PMID 26245868, 2015). "In addition, in an in vivo study in diabetic rats, they showed that KLF6 and PPAR-γ (localized downstream of KLF6) play a key role in the regulation of TXNIP expression in the development of diabetes mellitus." (PMID 24397367, 2014). "TXNIP has been shown to modulate inflammation and oxidative stress in β-cells, including IL-1β which is known to be a key mediator of islet dysfunction and destruction in diabetes." (PMID 23691179, 2013). "As thioredoxin interacting protein (TXNIP) was shown to contribute to impaired angiogenesis in diabetes, we investigated whether SN might inhibit TXNIP on mRNA level." (PMID 24086307, 2013). "Several components of the thioredoxin system are closely linked to LRRK2, including PRDX3, TXNIP, and TXNRD1, which have been identified in recent years as risk factors for obesity and diabetes in human subjects, and as nutrient sensing mechanisms and controlling factors of adipogenesis in mice." (PMID 23799078, 2013). "Notably, TXNIP null mice are resistant to diabetes, showing that TXNIP is necessary for the induction of insulin resistance." (PMID 22482078, 2012). "Moreover, we have shown that enhanced TXNIP expression in diabetes ultimately leads to neurodegeneration." (PMID 22482078, 2012).